CRP (C-reactive protein)
Diseases named in the same sentence as CRP in open-access papers (continued):
Sharing a sentence is not in itself a finding about the gene and the disease.
tumor (continued). "Various mechanisms appear to be involved, including the presence of tumour growth inducing inflammation and plasma CRP, as well as the tumours directly producing various inflammatory cytokines, including CRP, IL-6 and IL-8, which in turn induce hepatic CRP." (PMID 30662766, 2019). "In univariate analysis, T stage, N stage, TNM stage, tumor size, serum CRP level, PLR, maximum SUV, metabolic tumor volume, total lesion glycolysis, BM SUV, and BLR were significantly associated with disease progression-free survival (p < 0.05)." (PMID 31382679, 2019). "The diagnostic specificity of CXCL-8 levels (73%) was lower than that of the classical tumor markers and CRP." (PMID 30820705, 2019). "Their blood data including albumin and C-reactive protein for Glasgow Prognostic Score and cytokeratin 19 fragment 21-1 as a tumor marker were measured before starting treatment." (PMID 31038863, 2019). "Immunohistochemistry findings of the larger tumor showed that the hepatocytes were positive for C-reactive protein (CRP) and liver fatty acid-binding protein (LFABP) and negative for β-catenin, glutamine synthetase (GS), and glypican-3." (PMID 30798096, 2019). "A univariate logistic regression models of the CRP groups (CRP≤10 and >10) provided distinct p-values for each of the four tumour parameters, and MTD, AFP, and PVT were found to be statistically significant (p<0.05)." (PMID 30662766, 2019). "Among the variables that showed statistical significance in univariate analysis, TNM stage, tumor size, serum CRP level, PLR, maximum SUV, total lesion glycolysis, BM SUV, and BLR were selected for multivariate analysis." (PMID 31382679, 2019). "The CFS had the highest coefficient of determination (R2 = 0.188) to predict tumor recurrence of all composite scores, comprising CRP (R2 = 0.141) and fibrinogen (R2 = 0.158), the best single factor predictors." (PMID 31819103, 2019). "It is generally recognized that several factors, such as tumor length, vessel invasion, CRP, ALB, PALB, CAR, CPR, and TNM stage, were significantly associated with CSS in univariate analyses." (PMID 31379941, 2019). "Intriguingly, an antitumor effect has been described for CRP via inhibition of epithelial-mesenchymal transition and tumor-promoting M2 macrophages in preclinical studies." (PMID 31788452, 2019). "summarizes the descriptive statistics and comparisons of the NLR ratio, PLR ratio and CRP levels for each of the 4 tumour characteristics of MTD, AFP, multifocality and PVT patient groups." (PMID 30662766, 2019). "The median serum concentration of CRP was 21.6 mg/L and showed significant increase with pathological stage of the tumor." (PMID 31487965, 2019). "The CRP, an inflammatory marker, serves as an index for the immune status of the host and the degree of tumor progression." (PMID 31443339, 2019). "Fibrinogen (Fib), which is an essential protein in the coagulation cascade and an acute-phase reaction protein for systemic inflammation like C-reactive protein (CRP), plays an important role in tumor development." (PMID 31533857, 2019). "Among the classical tumor markers and CRP, the differences between TNM stages were statistically significant only for SCC-Ag levels." (PMID 30820705, 2019). "The percentage of elevated concentrations (diagnostic sensitivity) of CXCL-8 (86%) was higher than that of CRP (82%) and far higher than those of the classical tumor markers: SCC-Ag (74%) and CEA (18%)." (PMID 30820705, 2019). "Similar results were obtained for the OSCC and OAC subgroups, where the AUC of CXCL-8 was also lower than that of CRP and higher than those of the classical tumor markers." (PMID 30820705, 2019). "In our study, the preoperative predictive factors for pathological T3a upstaging were tumor diameter, CRP level, and AST/ALT ratio in univariate analysis." (PMID 31311108, 2019).
tumor (continued). "We revealed that in the total OC group, the AUC of CXCL-8 was lower than that of CRP, but higher in comparison with the AUCs of the classical tumor markers in OC diagnosis." (PMID 30820705, 2019). "It suggests that the detection of serum tumor markers in clinic should be combined with the detection of serum hs-CRP level." (PMID 31497547, 2019). "The laboratory parameter C-reactive protein (CRP) increased significantly, whereas there was a significant decrease in leukocyte count, hemoglobin, albumin and cholinesterase as well as in the tumor marker CA 19.9." (PMID 31717736, 2019). "Inflammation, cytokines and chemokines induce tumor proliferation, angiogenesis and metastasis by CRP and neutrophil induction." (PMID 30942057, 2019). "CRP levels were determined by immunoturbidimetric method, while classical tumor marker levels were measured using chemiluminescent immunoassay." (PMID 30820705, 2019). "In the present study, we established significant correlations between serum CXCL-8 concentrations, depth of tumor invasion (T factor) and CRP concentrations in OC patients and the OSCC subgroup." (PMID 30820705, 2019). "Laboratory findings included a routine blood examination, and a C-Reactive Protein (CRP) test, with tumor markers all found to be within normal ranges." (PMID 31174571, 2019). "The highest diagnostic sensitivity was obtained for the combined measurement of CXCL-8 and CRP (100%), and this value was higher than that for the combined measurement of the classical tumor markers (76%)." (PMID 30820705, 2019). "In our previous work we showed an association of systemic inflammatory proteins, such as CRP and fibrinogen and indices formed from inflammatory cell counts, such as NLR, with higher tumor stages and worse prognosis in patients with TETs17,18." (PMID 31819103, 2019). "A CRP level greater than 10 mg/L correlated with advanced tumor stage and reduced albumin and survival." (PMID 30941358, 2019). "In our study, age, tumor stage, UICC clinical stage, BMI, EBV DNA, CRP and PICC-VTE were found to be associated with PFS in univariable analysis." (PMID 30594171, 2018). "No abnormalities were found by chest or abdominal computed tomography (CT) or in the levels of tumor markers, C-reactive protein (CRP), antistreptolysin O (ASO) or rheumatoid factor (RF)." (PMID 30445952, 2018). "In multivariable analysis, CRP remained a strong predictor for overall survival when adjusted for AJCC tumor stage (HR 1.31 95%CI 1.02–1.57; p = 0.031)." (PMID 29701260, 2018). "Pearson correlation analysis showed a significant positive correlation between plasma protein concentrations and tumor size for CRP, C9, and LRG1." (PMID 29513714, 2018). "CRP has been shown to be a sensitive marker of inflammation and further has the ability to distinguish inflammatory states as a result of neoplasia, immune-mediated disease, surgery, and infections." (PMID 29843742, 2018). "It is reported that CRP promotes endothelial cell survival by acting on microglial cells and promoting tumor angiogenesis." (PMID 29513714, 2018). "Another serum biomarker which correlates with tumor burden is the acute-phase protein C-reactive protein (CRP)." (PMID 30002656, 2018). "A few biologic compounds meet the criteria for an ideal tumor marker; C-reactive protein (CRP) is one." (PMID 30138391, 2018). "In this study we demonstrated that PBMC killed tumor cells more efficiently when CRP was added to coculture in vitro." (PMID 30450100, 2018). "The tumour leads to an inflammatory response including increased serum levels of CRP on the one hand, and chronic inflammation can be involved in the development of a malignant process, on the other hand." (PMID 30539028, 2018). "The SSI and non-SSI groups significantly differed regarding surgical time, diameter of the skin incision, maximum tumor diameter, instrumentation, presence of an open wound, preoperative chemotherapy, preoperative C-reactive protein concentration, and GNRI." (PMID 30513989, 2018).
tumor (continued). "We recently demonstrated significantly increased CRP serum concentrations during the follow-up of patients who developed tumor recurrence." (PMID 29774108, 2018). "In a related context, the low pH found in tumor microenvironments and inflammatory sites has been shown to increase the binding affinity of CRP to certain ligands such as fibronectin, a protein found in abundance in tumors." (PMID 30450100, 2018). "Along with serum ferritin, ECOG-PS, tumor type, and CRP were the significant independent prognostic factors in advanced hepatobiliary cancer patients treated with KM." (PMID 29879960, 2018). "The plasma concentrations of LRG1, CRP, and C9 showed significant positive correlations with tumor size (R2 = 0.534, 0.495, and 0.452, respectively)." (PMID 29513714, 2018). "A fourth proposed mechanism cites the fact that tumor cells can produce CRP themselves, and they are also able to release cytokines such as IL-6 and IL-8, which contribute to the increase in CRP levels." (PMID 29668751, 2018). "GPx4-overexpressing cells displayed impaired tumor growth, reduced proliferation, altered angiogenesis and decreased expression of clinically relevant cytokine interleukin-8 and C-reactive protein." (PMID 29515790, 2018). "Vice versa, in anakoinosis-inducing trials, including pioglitazone, C-reactive protein response to anakoinosis-inducing therapy is indicating tumor response." (PMID 30424016, 2018). "We recently demonstrated that increased serum concentrations of C-reactive protein (CRP), heat shock proteins (HSPs), and high-mobility group box-1 (HMGB1) were associated with advanced tumor stage and worse outcome." (PMID 29774108, 2018). "Our results also indicate that ECOG-PS, tumor type, and CRP can be considered with serum ferritin in predicting prognosis in patients with advanced hepatobiliary cancers." (PMID 29879960, 2018). "CRP at baseline was significantly correlated with several other variables including age, function sum score, symptom sum score, performance status and tumor load." (PMID 28859644, 2017). "The correlation between elevation of CRP and clinicopathologic factors was more evident in the buccal cancer compared to other tumor subsites." (PMID 28209200, 2017). "The expression of TNFα, interleukin-6 and C-reactive protein were all increased in the livers of tumor-bearing mice, and KD significantly boosted their expression." (PMID 28915665, 2017). "The distribution of characteristics was significantly varied in T classification, tumor size, nuclear grade, tumor necrosis, C-reactive protein, UISS and SSIGN according to COP-NLR." (PMID 29299149, 2017). "After complete tumor resection CRP serum concentrations were decreased (p = 0.135) but increased significantly in case of tumor recurrence (p = 0.001)." (PMID 28514756, 2017). "The independent prognostic factors for skeletal metastasis (SMAD, SMFS) included N category, circulating EBV-DNA, LDH, ALP, HGB and CRP; each of these factors has been previously reported to play a vital role in tumor progression or metastasis." (PMID 28874126, 2017). "The elevation of CRP levels (≥5.0 mg/L) was significantly correlated with pathologic tumor status, pathologic nodal status, nodal extracapsular spread, tumor stage, skin invasion, tumor depth (≥10 mm), and bone invasion." (PMID 28209200, 2017). "Further, we analyzed the prognostic value of CRP/Alb combined with tumor stage and residual tumor mass." (PMID 28431566, 2017). "In our RCC model, the livers of engrafted mice exhibited a significant increase in CRP mRNA levels compared to tumor-free mice." (PMID 28915665, 2017). "In the multivariate analysis, growth pattern (pushing vs.ID: p = 0.02), CRP (p = 0.002), and tumor size (p = 0.01) were independent prognosticators for disease-specific survival." (PMID 28727824, 2017). "C-reactive protein levels, hemoglobin levels, and tumor grade were strongly correlated with IL-6 levels." (PMID 28851899, 2017).
tumor (continued). "Univariate analysis revealed a significant impact of the tumor size, lymph node involvement, nuclear grade, CRP, and PLR on DFS." (PMID 28489884, 2017). "CRP serum concentrations were also elevated in advanced tumor stages (III-IV) compared to early tumor stages (I–II; p = 0.002)." (PMID 28514756, 2017). "C-reactive protein also engages in complex, mutually-stimulating interactions with autophagy and it promotes proliferation and inhibits apoptosis of certain tumor cells." (PMID 29145436, 2017). "Soluble blood factors studied in CTLA-4 ICI-treated patients included S100, circulating tumor DNA, vascular endothelial growth factor, erythrocyte sedimentation rate, C-reactive protein, albumin, and lactate dehydrogenase (LDH)." (PMID 29034210, 2017). "Actually, inflammatory cells (such as neutrophils, lymphocytes, monocytes, and platelets) and proteins (such as CRP) are important functional factors because they take important parts in proliferation and metastasis of tumor cells." (PMID 27860387, 2017). "In case of tumor recurrence, postoperative CRP serum concentrations increased significantly (4.72 ± 1.61 mg/dL; p = 0.001)." (PMID 28514756, 2017). "All three KD groups displayed significantly enhanced expression of IL-6 and/or CRP in the liver of the tumor bearing mice." (PMID 28915665, 2017). "Univariate analysis revealed that lower CRP and PLR values as well as tumor size, lymph node involvement, and nuclear grade were significantly associated with superior DFS (CRP: P<0.01; PLR, tumor size, lymph node involvement, and nuclear grade: P<0.05)." (PMID 28489884, 2017). "CRP serum concentrations were significantly different according to clinical tumor stage (p = 0.003)." (PMID 28514756, 2017). "Our study revealed that NLR/Alb ratio was associated with tumor length (P < 0.001), TNM stage (P < 0.001), NLR (P = 0.021), CRP (P = 0.002), Alb (P < 0.001), CRP/Alb (P = 0.002) and GPS (P < 0.001), respectively." (PMID 29262582, 2017). "First, along with tumour recurrence and progression, the systemic inflammatory response (as reflected by serum CRP concentration) was increasingly activated during chemotherapy in patients not given FO-enriched nutrition." (PMID 28684736, 2017). "Univariate analysis for disease-specific survival confirmed the predictive value of growth pattern (pushing vs. ID: p = 0.004, pushing vs. IF: p = 0.08), CRP (p <0.0001), and tumor size (p = 0.005)." (PMID 28727824, 2017). "In our study, tumor cell growth was enhanced by releasates obtained from purified platelets stimulated with CRP." (PMID 28638139, 2017). "The diagnostic specificity for CXCL12 levels (80%) was lower than that for classical tumor markers and CRP, similarly to positive predictive value (PPV)." (PMID 27041792, 2016). "The diagnostic accuracy of CXCR4 (71%) was similar to CRP (72%), much higher in comparison to CXCL12 (59%) and classical tumor markers (CEA: 49%, SCC-Ag: 46%), and increased to 77% in combined measurement with CRP." (PMID 27041792, 2016). "If we analyze the relationship between serum levels of proteins tested and histological type of EC, the serum concentrations of CXCL12 were significantly higher in patients with ESCC than in control group, similarly to classical tumor markers and CRP." (PMID 27041792, 2016). "In terms of investigations, a bone profile, plain film radiographs, C-reactive protein, erythrocyte sedimentation rate, and tumor markers were all preformed and proved unremarkable." (PMID 27258509, 2016). "The concentrations of classical tumor markers as well as CRP were found to be higher in EC patients than in control group." (PMID 27041792, 2016). "Elevated CRP reflected increased systemic inflammatory response, which involved in tumor development and progression." (PMID 28008988, 2016).
tumor (continued). "A pro-inflammatory immune response to the tumor may cause a systemic inflammatory response in the host which can be detected in untreated patients before surgery by measuring preoperative increases in circulating protein levels such as C-reactive protein (CRP)." (PMID 26848624, 2016). "Second, a high level of CRP is known to contribute to a high tumor burden, extensive complications and poor prognosis in MM." (PMID 27129167, 2016). "If we consider the association between serum levels of proteins tested and histological type of EC, the concentrations of CXCL12 were significantly higher in patients with ESCC than in control group, similar to classical tumor markers and CRP." (PMID 27041792, 2016). "An elevated serum CRP level was significantly correlated with gender, advanced tumor stage, elevated ALT, AST, carcinoembryonic antigen (CEA), carbohydrate antigen 19-9 (CA19-9) levels and intraepithelial ductal spread (P < 0.05)." (PMID 27733196, 2016). "The present paper is continuation of our previous findings concerning the role of selected inflammatory proteins, such as C-reactive protein (CRP), interleukin 6 (IL-6), hematopoietic cytokines (HGFs), and metalloproteinases (MMPs) as tumor markers for EC." (PMID 27041792, 2016). "Several proinflammatory cytokines, such as interleukin-1 (IL-1), IL-6, and TNF-a, expressed by the tumor environment induce CRP synthesis from the liver and other tissues." (PMID 26880857, 2016). "Another point to discuss is that C-reactive protein can change with tumor burden, but many of the significant increases observed within a few weeks on treatment were seen with little change in overall tumor burden." (PMID 27008709, 2016). "For patients with resectable PDAC, preoperative CRP, along with albumin and tumour markers, is useful for predicting prognosis." (PMID 27632196, 2016). "The diagnostic accuracy of CXCR4 was similar to CRP, much higher than that for CXCL12 and classical tumor markers and increased to 77% in combination with CRP." (PMID 27041792, 2016). "The diagnostic sensitivity, negative predictive value, and accuracy of CXCR4 were the highest among all analyzed proteins and increased for combined analysis with classical tumor markers and CRP levels." (PMID 27041792, 2016). "On the other hand, CRP is also upregulated by cytokines such as IL-6 and tumor necrosis factor, and this upregulation is considered to be a systemic reaction to tumor progression." (PMID 25602444, 2015). "Interesting enough, subgroup analyses suggested the prognostic relevance of serum CRP was affected by maximal tumor size and tumor numbers." (PMID 25602444, 2015). "As compared to those with maximal tumor dimension≦ 5cm, odds ratio for CRP was significant from those with maximal tumor dimension> 5cm (P < 0.01 for interaction)." (PMID 25602444, 2015). "CRP is synthesized in hepatocytes in response to cytokines, particularly IL-6, released from leucocytes within the tumor microenvironment." (PMID 26693355, 2015). "There was a positive correlation between Hs-CRP and Child-Pugh class (r = 0.322, P < 0.0001), similar trend was also observed with respect to the correlation between Hs-CRP and tumor stage (r = 0.304, P < 0.0001)." (PMID 26656354, 2015). "In ER group, there was evidence for an interaction between serum CRP and the maximal tumor dimension." (PMID 25602444, 2015). "Positive correlations were found regarding preoperative serum Hs-CRP level and tumor size, Child-Pugh class, or tumor stage (all P < 0.0001)." (PMID 26656354, 2015). "The balance of evidence supports wider (and perhaps routine) use of CRP by oncologists for staging, assessment of tumor response and prognostication in at least these two tumor types." (PMID 26717416, 2015). "CRP-positivity develops a favorable microenvironment for the tumor cells through acute inflammatory cytokine network system maintenance." (PMID 26717416, 2015).